IL1A (interleukin 1 alpha)
Diseases named in the same sentence as IL1A in open-access papers (continued):
Sharing a sentence is not in itself a finding about the gene and the disease.
Stroke (continued). "While the role of IL-1β (main released isoform) has been well studied in stroke, the role of the IL-1α isoform remains largely unknown." (PMID 31727174, 2019). "Our previous work suggested that elements of the extracellular matrix, such as the heparan sulfate proteoglycan perlecan, are proteolyzed into smaller protein fragments after stroke, and that this process could partially be driven by IL-1α." (PMID 31727174, 2019). "We next investigated whether delayed/subacute IL-1α treatment enhances functional benefit when given 3 days following stroke." (PMID 31727174, 2019). "In stroke models, adult progenitor cell therapy leads to decreased tissue levels of pro-inflammatory cytokines such as interleukin-1 alpha (IL1α), interleukin-1 beta (IL1β), and TNF-α and interleukin-6 (IL-6) and increased levels of anti-inflammatory cytokine such as IL-10." (PMID 29548333, 2018). "In C57BL/6 mice at 7 weeks post-stroke there were increased levels of G-CSF, GM-CSF, IFNγ, IL-1α, IL-5, IL-6, IL-12 (p40), IL-12 (p70), IP-10, KC, MCP-1, MIP-1α, MIP-1β, MIP-2A, RANTES, and TNFα within the infarct compared to the equivalent area of cortex from sham mice." (PMID 27600707, 2016). "Historically, IL-1β was considered the primary ligand mediating an exaggerated response to ischemic injury however recent research indicates IL-1α also plays a crucial role in post-stroke pathogenesis and that it may proceed IL-1β expression." (PMID 25705177, 2015). "The main finding was that the association between the TT genotype and T allele of IL-1α-889 and IS was mainly limited to stroke patients with LAA, but not for those cases with CE, SVD." (PMID 24063019, 2013). "However, in the sub-acute phase (7 d reperfusion) following stroke, TREM2-KO mice showed a decreased transcription of pro-inflammatory cytokines TNFα, IL-1α and IL-1β, associated with a reduced microglial activity (CD68, Iba1)." (PMID 23301011, 2013). "Furthermore, TNF-α, IL-1β, IL-1α, and Cox-2 are well-studied cytokines related to inflammatory responses in stroke, and both appear to exacerbate ischemic damage." (PMID 22719787, 2012). "Furthermore, experimental stroke induced a 4-fold up-regulation of IL-1α and 4.8-fold increase in IL-1β expressing NKCC1 KO microglia cells compared to WT animals, while the overall microglia density and the number of activated microglia were not different at 24-hour reperfusion." (PMID 35085235, 2022). "Importantly, we found that IL‐1α was abundantly expressed in the lungs of the sham‐operated mice relative to other cytokines we measured (~50 pg/mg of tissue), but its level was significantly reduced at both 24‐ and 72‐hour time points postischemic stroke." (PMID 31691533, 2019). "Thus, IL-1α is present early in stroke pathogenesis, modulates brain endothelial cell angiogenesis, and could, therefore, be a prominent component of the brain’s response to ischemic injury." (PMID 31727174, 2019). "To determine whether perlecan is required for the acute neuroprotective effects of IL-1α after stroke, we used a perlecan hypomorph (pln KO) mouse that expresses 10% of normal total perlecan levels (and hence 10% of normal total perlecan LG3; complete perlecan knockout mice are embryonic lethal)." (PMID 31727174, 2019). "Genes related to inflammation such as Ccl5, Cxcl5, Il1a, Tnfsf10, Nfkb1, Tnfrsf1b, Ccr7, Tnfrsf9, Ccl7, Il1b, Il6, and Ccl24 were also downregulated upon MMP-3 KO in male stroke brains." (PMID 39000490, 2024). "Recent studies suggest beneficial effects of ES in a rat model of stroke, in which mesencephalic electric stimulation attenuated the expression of inflammatory cytokines, IFN-γ, TNF-α, and IL-1α, in the perilesional area of stimulated rats." (PMID 36158207, 2022). "Depletion of IL-1α or IL-1β attenuated BBB disruption and decreased infarct size in experimental stroke." (PMID 34248961, 2021).
Stroke (continued). "We prevented “A1” neurotoxic astrocyte formation after stroke withtriple knockout (TNF-, Il-1a-, and C1q-) mice, and compared their neuroinflammatory responseand stroke size to wildtype mice." (PMID 34612709, 2021). "Expression of IL-1α and IL-6 significantly increased after DCAL and was also the most upregulated in the stroke models." (PMID 33097782, 2020). "In an attempt to separate the neuroprotective effects of IL-1α from its neuroreparative effects, in these experiments we delayed IL-1α administration until PSD3, a time point at which the ischemic infarct is maximally evolved in our stroke model." (PMID 31727174, 2019). "Canonically, IL-1α is not cleaved until severe injury to the cell or cell death, which occurs in the ischemic core and penumbra after stroke." (PMID 38543098, 2024). "Many inflammatory factors and chemokines were upregulated in IL-1α-, TNFα- and C1q-treated astrocytes, indicating that A1 astrocytes may induce inflammatory and immune responses to disrupt BBB integrity after stroke." (PMID 35656116, 2022). "Astrocytes can increase neutrophil recruitment via CXCL chemokines, express adhesion molecules for leukocyte recruitment, which can be stimulated by IL-1, and further intensify pro-inflammation by producing cytokines such as IL-1α and TNF-α after ischemic and reperfusion injury of stroke." (PMID 34502395, 2021). "IL-1α-primed MSC-derived conditioned medium treatment led to ∼30% reduction in lesion volume and improved behavioral outcomes and neurological score in a mouse model of stroke." (PMID 33869170, 2021). "In line with our studies, plasma IL-1α did not change after stroke, suggesting that peripheral IL-1α production does not contribute to post-stroke neuroinflammation." (PMID 32503645, 2020). "Additionally, more studies (potentially in animals with impaired post-stroke angiogenesis or neurogenesis capabilities) are necessary to determine whether both of these observations are merely correlative with- or also contribute to IL-1α’s therapeutic benefits." (PMID 31727174, 2019). "Previous reports characterized an acute immune response to ischemic stroke by profiling certain cytokines and chemokines (e.g., IL-1α and β, IL-6, IL-8, IL-9, IL-10, IL-12, IL-18, TNFα and soluble TNF-receptors p55, p75 and GRO-α) in the sera or cerebrospinal fluid of stroke patients." (PMID 31164999, 2019). "We now show in the mouse stroke models (transient tandem ipsilateral common carotid artery (CCA) and middle cerebral artery occlusion (MCA) occlusion, MCA suture occlusion) that IL-1α is neuroprotective when acutely given either intravenously (IV) or IA at low sub-pathologic doses." (PMID 31727174, 2019). "Even more interestingly, these effects become more pronounced with IV or IA IL-1α treatment, but not in vehicle controls, with increased time after stroke." (PMID 31727174, 2019). "Additionally, since it is known that IL-1α is readily transported across the BBB, coupled with the well-documented post-stroke disruption of the BBB, we are confident that at least some of the administered IL-1α was taken up into the brain parenchyma." (PMID 31727174, 2019). "In order to determine and compare the potential inflammatory systemic effects of IA and IV IL-1α delivery, we evaluated levels of known pro-inflammatory cytokines in the serum of mice recovering from stroke with or without IL-1α treatment." (PMID 31727174, 2019). "Taken together, we found that, regardless of treatment modality, acute IL-1α treatment improves functional outcomes after stroke." (PMID 31727174, 2019). "In addition, IL1A, IL6, TNF and other anti-stroke targets were also presented an up-regulated trend." (PMID 27672514, 2016). "However, after sex stratification we found that IL1A, IL1B, IL6, IL8, TNF and other 13 anti-stroke targets were all up-regulated in male patients." (PMID 27672514, 2016).
Stroke (continued). "The induction of IL-1α, IL-1β, TNFα MCP-1, RANTES, G-CSF, KC mRNA and increased MCP-1, RANTES, G-CSF protein levels in the brain after systemic LPS challenge are likely to result in a primed proinflammatory response by the time experimental stroke is induced." (PMID 22114895, 2011). "Similarly, the IL1α concentration was around two times higher 7 days after stroke than before stroke; however, this was without statistical significance (34.04 ± 13.3 pg/mL)." (PMID 40332314, 2025). "In the future study, analyzing additional markers for inflammatory MG, such as CD16 and IL-1α, and anti-inflammatory MG, such as Arg1 and YM1, would further strengthen the essential role of endogenous Nrf2/HO-1 axis activation in modulating MG polarization after stroke." (PMID 39469715, 2024). "Thus, it is possible that IFNAR1 signaling induces STAT3 activation, leading to the suppression of tPA-enhanced inflammatory molecules, IL-1α, IL-1β and CD86, expression and the promotion of anti-inflammatory molecules, Arg1 and CD206, upregulation in MG in delayed tPA-treated stroke animals." (PMID 37063896, 2023). "Importantly, the delayed IL-1α treatment paradigm was validated in two different stroke models in two different labs, meeting an important criterion for the STAIR recommendations for the testing on experimental stroke treatments." (PMID 31727174, 2019). "In both stroke models, both treatment groups showed similar functional deficit in their total scores on the days following stroke surgery as expected (filament MCAo 28-point score: vehicle: 10.57 ± 1.39 vs. IL-1α: 10.60 ± 1.24 points, tandem CCA/MCA model not shown)." (PMID 31727174, 2019). "We then collected serum from the same animals 24 h post-stroke/treatment and then again upon sacrifice at PSD 7 to evaluate if there were effects on pro-inflammatory cytokine levels in the serum in response to not only the stroke but also in response to IL-1α injection." (PMID 31727174, 2019). "Importantly, IL1A, ILAB, IL6 and TNF and other anti-stroke target genes were up-regulated in males." (PMID 27672514, 2016). "With regard to the selected participants for comparing serum IL-1α and IL-1β concentrations, we could not determine whether there was a high proportion of stroke patients with CE, SVD, or any other determined etiology." (PMID 24063019, 2013). "Indeed, TNFα, IL-1α, IL-1β, CCL2, CCL3 and CX3CR1 transcript expression differed in the ischemic cerebral tissue of TREM2-KO mice compared to littermate controls at day 7 after stroke." (PMID 23301011, 2013). "In our experimental stroke studies, we could not detect increased cytokine production in the absence of microglial NKCC1 early (8 hours) after MCAo, while both IL-1α and IL-1β expression were markedly up-regulated in NKCC1 KO microglia 24 hours after reperfusion." (PMID 35085235, 2022).
Obesity (55 papers, 2010 to 2025). Accumulation of substantial excess body fat. "The study reported associations between smoking, obesity, and altered expression of inflammatory markers such as IL-1α, CDCP1, TRAIL, and CD6." (PMID 40426647, 2025). "Obesity-related DN is closely associated with chronic, low-grade inflammation and cytokine expression (IL-1α, IL-6, TGFβ, and TNFα), leading to leukocyte recruitment and DN." (PMID 41369384, 2025). "The results indicated that IL1A -889C > T (rs1800587) was a functional polymorphism of IL1A associated with obesity." (PMID 35139823, 2022). "A KO of the IL1 receptor type 1 gene (Il1r1), which codes for a receptor of IL-1α, IL-1β, and IL-1RN, causes maturity onset obesity on a normal diet but reduces local adipose-tissue inflammation on an HFD despite almost unchanged immune-cell recruitment." (PMID 34834553, 2021). "To delineate the specific role of IL-1α in obesity, we found an apparent association between IL-1α polymorphisms (rs1800587 and rs17561) and BMI in obese women and the effect of the IL-1α variant on transcriptional activity." (PMID 22216303, 2011). "However, HFD-induced obesity was associated with higher plasma IL-1α levels, and IL-1α deficiency reduced adiposity, glucose intolerance, and hepatic lipogenesis in HFD-induced obesity in mice." (PMID 36717684, 2023). "IL-1 family, including IL-1α and IL-1β, is considered the most key cytokine associated with the pathogenesis of OA that induces the inflammatory catabolic process combined with other catabolic factors such as aging, obesity, and traumatic joint injury." (PMID 33833854, 2021). "IL-1α C-889T (rs1800587) is a functional polymorphism of IL-1α associated with obesity." (PMID 22216303, 2011). "We also hypothesized that the increased/decreased expression of IL-1α as a consequence of IL-1α C-889T (rs1800587) and IL-1α G+4845T (rs17561) polymorphisms could be a factor in obesity." (PMID 22216303, 2011). "In this study, we investigated whether polymorphisms in IL-1α contribute to human obesity." (PMID 22216303, 2011). "IL-1α and IL-1β exacerbate IR in obesity by impairing adipocyte function and promoting inflammation." (PMID 38622732, 2024). "Interleukin 1 alpha (IL1A) is a member of the interleukin 1 cytokine family that is involved in the molecular mechanisms of hypertension, diabetes, obesity, and lung cancer." (PMID 36685671, 2023). "TLR3 and TLR7 KOs were found to be protective against HFD induced obesity and weight gain and IL1a-KO reduces adiposity, which reflects predicted gene changes in CR20-HFD males compared to FED-HFD." (PMID 38720938, 2023). "Two studies compared IL-1α levels among participants with eating disorders, obesity and normal weight controls." (PMID 35911732, 2022). "IL-1α is an important inflammatory mediator and regulates micro-inflammation observed in participants with obesity and/or diabetes." (PMID 35586621, 2022). "Since adipocyte death is increased in adipose tissue during obesity, IL-1α plays a pivotal role in the initiation of adipose tissue inflammation during obesity by promoting the chronic inflammation typical of MetS." (PMID 35743665, 2022). "Certain inflammatory enzymes like interleukin-2 (IL-2), interleukin-10 (IL-10), interferon-γ (IFN-γ), and interleukin 1-α (IL1-α) were found to differ between participants with obesity and with normal BMI." (PMID 36612361, 2022). "Palmitic acid has been associated with increased IL-1 signaling, and elevation of serum IL-1α has been reported in HFD-induced obesity in mice." (PMID 24156623, 2013). "Compared with a number of reports on the role of IL-1β as an endogenous mediator of insulin resistance, studies on the relationship between IL-1α and insulin signaling and obesity are rare." (PMID 22216303, 2011). "Since IL-1α is correlated with obesity in the in vivo study, we wished to determine if IL-1α affected the differentiation process of adipocytes." (PMID 22216303, 2011).
Obesity (continued). "Of note, the pathophysiological link between obesity and resulting T2D mediated by IL-1α, IL-1β, and their antagonist IL-1ra is discussed in current literature, but is not completely understood." (PMID 20169140, 2010). "In our study the significant increase of IL-1α in SSPN−/− after chronic exposure to obesity-promoting conditions and heightened levels of its regulator IL-1Ra in WT may underlie the temporal differences in WAT inflammation seen between these groups." (PMID 39120469, 2024). "Since the previous reports demonstrated the alteration of IL1A, CCL5, and OX40 in the Lkb1-deficient DC and expression of those genes are also well known to regulate adipose tissue inflammation in obesity, we examined the expression of those essential genes on ATM and ATDC." (PMID 36781473, 2023). "Moreover, elevated levels of serum IL1α were found not only in obese mice, but also humans with obesity." (PMID 34207683, 2021). "IL1α is the least studied of all three Il1R ligands in terms of obesity." (PMID 34207683, 2021). "Other extra-hepatic cell types such as adipocytes could also be important sources of IL-1α and IL-1β during NAFLD associated with obesity." (PMID 31507607, 2019). "Interestingly, levels of IL-1α inversely correlated with obesity and biliary injury and as disease severity increased, IL-1α levels tended to decrease." (PMID 29449577, 2018). "Certain cytokines, which are elevated in obesity such as TNF-α or IL-1α are able to induce PAR2." (PMID 28101054, 2016). "Indeed, pro-inflammatory adipokines, which are upregulated in obesity, such as IL-1α, IL-1β, and TNF-α have been described as potent PAR2 inducers in the vasculature." (PMID 28101054, 2016). "Activation of caspase-1 is required for optimal IL-1α and IL-1β maturation and secretion, with growing evidence implicating uncontrolled caspase-1 activation to be responsible for the pathophysiology of obesity and type 2 diabetes." (PMID 25849717, 2015). "LPS and IL-1α, which are elevated in obesity, upregulate MnSOD in 3T3-L1 cells." (PMID 24475187, 2014). "To examine whether the IL-1α is correlated with obesity in vivo, we measured the levels of IL-1α from serum of HFD-induced obese mice." (PMID 22216303, 2011). "The significant associations between osteoarthritis severity and serum leptin, adiponectin, and IL-1α concentrations, independent of diet and adiposity, support the role of systemic adipokines as mediators of obesity-associated osteoarthritis." (PMID 20604941, 2010). "A study using IL-1α KO mice suggests that a deficiency and/or reduction in IL-1α might exert a protective effect against HED diet-induced obesity and its metabolic consequences through a finding of decreased adipose tissue weight and glucose intolerance in the knockout mice." (PMID 40218905, 2025). "It is also possible that this connects to increased disease severity after respiratory viral infections in people with heightened inflammation such as inflamaging or obesity, where cytokines such as IL-1α and TNF-α could be increased in the mucosa before infection." (PMID 39127259, 2024). "Obesity was associated with decreased serum levels of Eotaxin and KC, and elevated serum levels of G-CSF, TNF-α in offspring mice, while KD alone was associated with elevated serum levels of G-CSF, IL-1b, IL-6, RANTES, TNF-α and decreased serum levels of IL-1a, IL-9, IL-12 (p70)." (PMID 37686855, 2023). "Similarly, mice deficient in IL-1α are protected against obesity-induced glucose intolerance; therefore, the blockade of IL1R1 and IL-1α could be used in the treatment of IR and obesity." (PMID 32012695, 2020). "A hypothesis to reconcile this unexpected observation is that IL-1α is a homeostatic regulator that opposes excess positive energy balance, wherein elevated IL-1α levels in obesity reflect inadequate compensation, analogous to what occurs with the adipokine leptin." (PMID 22216303, 2011).